PDCD1 (programmed cell death 1)
Diseases named in the same sentence as PDCD1 in open-access papers (continued):
Sharing a sentence is not in itself a finding about the gene and the disease.
infection (continued). "Although the precise meaning of these findings in effector CTLs vs. other populations is difficult to determine, the unique modulation in Pdcd1 nuclear positioning suggests ongoing changes and a distinct PD-1 configuration in LCMV-specific CTLs during infection." (PMID 39083377, 2024). "Although we observed by flow cytometry an upregulation of PD-1 in both CD4+ and CD8+ T cells and in Pdcd1 gene expression during the acute phase of infection, its antibody-mediated blockade failed to enhance parasite clearance in AT." (PMID 34525131, 2021). "The CD28 family member programmed cell death 1 (PD-1) has been shown to be the most highly expressed inhibitory receptor on CD8+ T cells during chronic infection, and to have a major role in regulating T cell exhaustion during infection." (PMID 23289632, 2013).
hematologic malignancies (16 papers, 2015 to 2025). "In hematological malignancies, common immune checkpoint targets are reported mainly include PDCD1, IDO1, PD-L1, LAG3, and CTLA-4." (PMID 36061194, 2022). "Immune checkpoints, such as programmed cell death 1 (PD-1), its ligand (PD-L1), and cytotoxic T lymphocyte antigen 4 (CTLA-4), have been extensively studied because of their overexpression in many solid tumors and hematological malignancies." (PMID 39555073, 2024).
immune dysfunction (9 papers, 2016 to 2025). "In contrast, the NC sample (cHC-1L) displayed a more robust immune-infiltrated phenotype, but with signs of immune dysfunction; the expression levels of T-cell exhaustion markers like PDCD1 and CTLA4 were significantly higher than in the CC sample (P < 0.0001)." (PMID 41235234, 2025). "Inhibitory pathways including the programmed cell death-1 (PD-1)/programmed death ligand-1 (PD-L1) interaction, cytotoxic T-lymphocyte-associated antigen 4 (CTLA-4) and killer cell immunoglobulin-like receptors (KIR) have also been shown to play important roles in MM immune dysfunction." (PMID 32138182, 2020). "Additionally, these patients showed upregulation of immune exhaustion markers such as LAG3, PDCD1, TIGIT, CTL4, and C-ECM, TITR signatures, indicating a state of immune dysfunction." (PMID 38951896, 2024).
adenocarcinoma (8 papers, 2020 to 2025). A common cancer characterized by the presence of malignant glandular cells. "The MC-38 adenocarcinoma cell line was transplanted into wild-type (Pdcd1+/+/Crbn+/+), Pdcd1+/+/CrbnI391V/I391V, and Pdcd1SD/SD/CrbnI391V/I391V mice to examine the effects of the oral administration of IBR on endogenous PD-1 degradation in vivo." (PMID 40687785, 2025). "By applying anti PD-1 (programmed cell death-1) and PD-L1 (programmed cell death ligand-1) immune checkpoint inhibitor treatment, unprecedented long survival could be achieved in both adenocarcinoma (ADC) and squamous cell carcinoma (SCC) subtypes of NSCLC." (PMID 37274772, 2023). "Immune checkpoint blockade (ICB) gene analysis further revealed significant upregulation of LAG3, PDCD1, PDCD1LG2, HAVCR2, and CD274 in the solid pattern adenocarcinomas." (PMID 38505588, 2024).
infectious disease (8 papers, 2018 to 2026). A disorder directly resulting from the presence and activity of a microbial, viral, or parasitic agent in humans. "Furthermore, both CD8Tex_PDCD1 and CD8Trm_LAG3 cells in COPD airways upregulated the pathways associated with protein synthesis and processing, such as infectious disease, ribosome biogenesis, translation, and SRP-dependent cotranslational protein targeting to membrane." (PMID 40589761, 2025).
hematologic tumors (3 papers, 2018 to 2025). "Nivolumab (Nivo), an antibody targeting the programmed cell death-1 (PD-1) checkpoint, is approved to treat several solid and hematologic tumors." (PMID 30400835, 2018).
head and neck tumor (1 paper, 2015). "We also show that a cluster of chemokine receptor genes at chromosome 3p2 is lost in head and neck tumor patients selected for reduced expression of PDCD1-linked T cell genes." (PMID 26398410, 2015). "Likewise, head and neck tumors with elevated levels of PDCD1.mod genes were associated with better patient survival." (PMID 26398410, 2015). "Likewise, our demonstration of improved survival in a subset of head and neck tumor patients with elevated levels of PDCD1-linked gene expression and alterations at chromosome 3p2 suggests that this is a population of head and neck tumor patients who may benefit from anti-PDCD1/PD-L1 therapy." (PMID 26398410, 2015). "Likewise, head and neck tumor samples differing in expression of the T/NK cell module PDCD1.mod showed highly significant copy number differences of genes at chromosome 3p2." (PMID 26398410, 2015).
PDCD1 also shares sentences with these, for which no sentence is quoted: metastatic carcinoma (9 papers); biliary tract cancer (8); mismatch repair deficiency (7); cholangiocarcinoma (6); lung squamous cell carcinoma (6); malignant pleural mesothelioma (6); classical Hodgkin lymphoma (5); vitiligo (5); gastroesophageal junction adenocarcinoma (4); GI tumors (4); graft versus host disease (4); HIV-1 infection (4); multiple sclerosis (4); cardia (3); cutaneous squamous cell carcinoma (3); diffuse large B-cell lymphoma (3); fibrosis (3); Hypertension (3); intrahepatic cholangiocarcinoma (3); lymphopenia (3); metabolic disorders (3); prostate tumor (3); soft tissue sarcoma (3); type 2 diabetes (3); Addison’s disease (2); adrenal crisis (2); Alzheimer disease (2); autoimmune thyroid disease (2); bacterial infection (2); bladder transitional cell carcinoma (2).
A further 180 diseases each share a sentence with PDCD1 in 2 papers or fewer.